ACSL4 (acyl-CoA synthetase long chain family member 4)
Diseases named in the same sentence as ACSL4 in open-access papers (continued):
Sharing a sentence is not in itself a finding about the gene and the disease.
breast cancer (continued). "ACSL4 in tumor lesions can be used as a predictive factor of complete pathological remission and progression-free survival of neoadjuvant chemotherapy in breast cancer." (PMID 36467032, 2022). "In breast cancer cells, ACSL4 is required for the cellular uptake of polyunsaturated fatty acids (PUFA) and is implicated in promoting breast cancer phenotypes, such as migration and invasion." (PMID 35448537, 2022). "In certain tumor cells, for example, kidney cancer and breast cancer cells, ACSL4 is highly expressed." (PMID 35743814, 2022). "ACSL4 plays a crucial role in mediating the radio-resistance of breast cancer through its regulation of FOXM1, an extensively studied transcription factor that is associated with the majority of malignancies." (PMID 36497375, 2022). "ACSL4, as a crucial molecule that regulates ferroptosis, is preferentially expressed in a group of basal-like breast cancer cell lines, and its expression appears to be closely associated with sensitivity to RSL3-induced ferroptosis." (PMID 35910359, 2022). "Further, the prognostic value of ACSL4 in different cancers was evaluated in these databases, and we found that the prognosis of ACSL4 in breast cancer and lung cancer was consistently poor." (PMID 35126480, 2022). "In breast cancer, ACSL4 promotes breast cancer cell proliferation, invasion and migration through the same mechanism." (PMID 35126480, 2022). "The two data sets were consistent: high expression of ACSL4 in colorectal cancer and liver cancer, low expression in breast cancer and central nervous tumor." (PMID 35126480, 2022). "In conclusion, these results suggested that higher expression of ACSL4 was a predictor of better prognosis of breast cancer." (PMID 35910359, 2022). "The deletion of SUFU can increase the ferroptosis of breast cancer cells activated by RSL3 by decreasing ACSL4." (PMID 36467032, 2022). "One of these reports indicated that ACSL4 is part of the mechanism responsible for the promotion of breast cancer cell proliferation, invasion, and migration." (PMID 35237519, 2022). "For example, acyl-CoA synthetase long-chain family member 4- (ACSL4-) dictated ferroptosis in breast cancer cells is accompanied by changes in mitochondrial morphology." (PMID 34211625, 2021). "ACSL4 upregulation in breast cancer, liver cancer, and colorectal cancer was reported to be related to recurrence and metastasis, and inhibiting ACSL4 in liver cancer cells attenuated cell growth." (PMID 34053456, 2021). "A previous study showed that some ferroptosis-related genes had the potential to be promising treatment targets in breast cancer, such as iron, ACSL4, GPX4, SLC7A11 and SLC3A." (PMID 33672990, 2021). "The results of this study collectively demonstrated that Polyphyllin III exerts its anticancer effect by inducing ferroptosis via ACSL4 in MDA-MB-231 breast cancer cells." (PMID 34040532, 2021). "Acyl-CoA synthetase long-chain family member 4 (ACSL4) functions as the acylase of arachidonic acid (AA) and is responsible for the proliferation, invasion and migration of certain breast cancer cells." (PMID 34040532, 2021). "Based on these results together, this study demonstrated that Polyphyllin III induced ferroptosis via ACSL4 in MDA-MB-231 breast cancer cells." (PMID 34040532, 2021). "In breast cancer, ACSL4 has been reported to be preferentially expressed in a panel of basal-like breast cancer cell lines and promote ferroptosis by enriching cellular membranes with long polyunsaturated n-6 fatty acids." (PMID 33292585, 2020). "Subsequently, they found that ACSL4 promoted cell chemo-resistance in breast cancer cells by regulating expression of transporters involved in drug resistance via the mTOR pathway." (PMID 33292585, 2020). "By contrast, increased expression of ACSL4 promoted an invasive phenotype in oestrogen receptor-positive mammary carcinoma cells and increased cell proliferation and tumour formation abilities." (PMID 32357142, 2020).
breast cancer (continued). "We established for the first time that estrogen-related receptor alpha (ERRα) is a transcription factor involved in the higher activation of the human ACSL4 promoter in breast cancer cells." (PMID 31311992, 2019). "The construction pNL1.1-1681 carrying a fragment of ~1.8 kb in length of the human ACSL4 promoter which contains also most of the exon 1 sequence was analyzed by transient transfection in breast cancer cell lines." (PMID 31311992, 2019). "The results presented in this manuscript demonstrated transcriptional mechanism is involved in the different expression of ACSL4 in human breast cancer cell lines of different aggressiveness." (PMID 31311992, 2019). "Our studies have rendered a successful characterization of the human ACSL4 promoter and different mechanisms regulating its action in breast cancer cells." (PMID 31311992, 2019). "In particular, although the role of ACSL4 mediating an aggressive phenotype in breast cancer is well accepted, the regulation mechanisms involved in its overexpression in TNBC have not been elucidated yet." (PMID 31311992, 2019). "Previous reports have established an inverse relationship between the expression of ACSL4 and ERα in breast cancer, as shown both in cancer cell lines and patients’ breast tumors, and indicate that ACSL4 negatively modulates the expression of ERα3,5,9." (PMID 31311992, 2019). "In conclusion, the results presented in this manuscript demonstrate that the different expression of ACSL4 in human breast cancer cell lines of different aggressiveness is at least partly due to a different transcriptional regulation." (PMID 31311992, 2019). "Here we demonstrate for the first time that differential transcriptional activity is involved in the regulation of ACSL4 expression in breast cancer cell lines." (PMID 31311992, 2019). "We cloned and functionally characterized the human ACSL4 promoter in breast cancer cell lines and was functional in all the lines studied, exhibiting greater activity in TNBC cells." (PMID 31311992, 2019). "Silencing ACSL4 in breast cancer cells affects the components of cell membranes, especially arachidonic acid." (PMID 30388870, 2018). "Recent studies reported that acyl‐CoA synthetase 4 (ACSL4) also plays a mediated role in occurrence of tamoxifen resistance via interrupting mTOR signal pathway in breast cancer." (PMID 28272775, 2017). "Real-time PCR verified the increased expression of CA9 and decreased expression of BIRC3 and ACSL4 in the breast cancer cell line." (PMID 27478411, 2016). "NSC87877, a specific inhibitor of the tyrosine phosphatase SHP2, has been shown to reduce Acsl4 protein levels in Acsl4-rich breast cancer cells and steroidogenic cells." (PMID 27375556, 2016). "Although the role of ACSL4 in mediating an aggressive phenotype in breast cancer is well accepted, the mechanism involved in this effect has yet to be fully elucidated." (PMID 26536660, 2015). "For this reason, the goal of this work was to study the signaling pathways triggered by ACSL4 overexpression which mediate cell phenotype change from mildly aggressive to highly aggressive in breast cancer cells." (PMID 26536660, 2015). "In both breast cancer cells and human arterial smooth muscle cells forced expression of ACSL4 results in increased accumulation of prostaglandin E2 (PGE2), and prostaglandins have been implicated in PCa." (PMID 26636648, 2015). "Functionally, we and others have found that ACSL4 is part of the mechanism responsible for increased breast cancer cell proliferation, invasion and migration, both in vitro and in vivo." (PMID 26536660, 2015). "The data with respect to breast cancer suggest that ACSL4, when co-expressed with estrogen receptor, is indicative of resistance to hormone-based targeted treatments in breast cancer." (PMID 26636648, 2015). "We show here that rapamycin and rosiglitazone, an ACSL4 inhibitor, can act in combination to inhibit cell growth in breast cancer cells." (PMID 26536660, 2015).
breast cancer (continued). "We have previously demonstrated an inverse relationship between sex steroid receptor(s) (AR and ER) expression and ACSL4 expression in both breast cancer and PCa." (PMID 26636648, 2015). "We showed that in both breast cancer cell lines and tumor samples, ACSL4 expression is inversely correlated with ER and AR levels." (PMID 24155918, 2013). "Studies assessing the effect of ACSL4 expression in breast cancer cell lines suggest that ACSL4 functions as a mediator of hormone independence and resistance to hormonal and chemotherapy." (PMID 24155918, 2013). "Recent studies have addressed the mechanism by which ACSL4 induces an aggressive phenotype in breast cancer." (PMID 24155918, 2013). "The precise role of ACSL4 activity in generating the malignant phenotype seen in colon, liver and aggressive breast cancers remains to be determined." (PMID 24155918, 2013). "In a study of 71 different breast cancer cell lines, ACSL4 status predicted QNBC status with a sensitivity of 78% and a specificity of 86%." (PMID 24155918, 2013). "The purpose of this study was to determine the role of long-chain fatty acyl-CoA synthetase 4 (ACSL4) in breast cancer." (PMID 24155918, 2013). "We have previously demonstrated that the fatty acid metabolic enzyme, long chain fatty acyl-CoA synthetase 4 (ACSL4) is differentially expressed in human breast cancer samples as a function of expression of ER and AR." (PMID 24155918, 2013). "An analysis of the expression of ACSL4 in breast cancer indicates that there is an inverse relationship between the presence of this lipid metabolic enzyme and the steroid hormone/HER2 receptor status of the sample." (PMID 24155918, 2013). "The MCF-7 Tet-Off/ACSL4 human breast cancer cells showed a significant reduction in ERα and PR, mRNA and protein expression (B and D respectively)." (PMID 22808264, 2012). "Abnormal expression of acyl-CoA synthetase-4 (ACSL4) has been documented in colon adenocarcinoma, hepatocellular carcinoma and breast cancer." (PMID 22808264, 2012). "In addition, esterification of AA by acyl-CoA synthetase-4 (ACSL4) may play a causal role in the aggressive phenotype of breast cancer cells through the compartmentalization of AA release in mitochondria, a mechanism that serves to drive the specific lipoxygenase metabolism of AA." (PMID 22811918, 2012). "Immunohistochemical analysis of tumor from MCF7-Tet-Off/ACSL4 breast cancer cells showed few positive cells expressing ER and very few stained for PR." (PMID 22808264, 2012). "We found that levels of LOX and COX-2 products of AA are regulated by ACSL4 expression in a breast cancer cell line." (PMID 22808264, 2012). "MDA-MB-231 breast cancer cells were treated with all possible combinations of two different inhibitors of ACSL4, LOX-5 and COX-2." (PMID 22808264, 2012). "Treatment of the MCF-7 Tet-Off/ACSL4 human breast cancer cells with doxycycline for 96 h return the levels of ERα and PR mRNA and protein expression to the levels of MCF-7 Tet-Off empty vector (control cells)." (PMID 22808264, 2012). "First of all, in our model we used a derivative of the MCF-7 breast cancer cell line (ER+ and PR+) that overexpresses ACSL4 in stable manner." (PMID 22808264, 2012). "Inmunohistochemical analysis of the tumor from animal inoculated with MCF-7 Tet-Off/ACSL4 breast cancer cell showed few positive cells expressing ERα and a very few stained for PR." (PMID 22808264, 2012). "With the use of this alternative xenogenic model, we further demonstrated that ACSL4 expression can be silenced in order to reduce the aggressiveness of the cell line and possibly the ability of cells to develop into mammary tumors." (PMID 22808264, 2012). "Functionally, we found that ACSL4 is part of the mechanism responsible for increased breast cancer cell proliferation, invasion and migration." (PMID 22808264, 2012).
breast cancer (continued). "This suggestion is supported by the experiments showing that treatment of the animal inoculated with MCF-7 Tet-Off/ACSL4 breast cancer cells with doxycycline reduced the tumor volume and the remainder cells became positive for the expression of ER and PR." (PMID 22808264, 2012). "This, in turn, suggests that ACSL4 regulates the breast cancer cell phenotype through the production of lipooxygenase and cyclooxygenase metabolites." (PMID 21085606, 2010). "Functionally, we found that ACSL4 is part of the mechanism responsible for the increase in breast cancer cell proliferation, invasion and migration." (PMID 21085606, 2010). "In fact, ACSL4 overexpression has been reported in colon adenocarcinoma, hepatocellular carcinoma and breast cancer." (PMID 21085606, 2010). "We found that ACSL4 is a key enzyme in the mechanism of intramitochondrial AA generation and in the production of lipooxygenase and cyclooxygenase metabolites of AA in breast cancer cells." (PMID 21085606, 2010). "In human breast cancer, ACSL4 is differentially expressed as a function of estrogen receptor alpha status." (PMID 21085606, 2010). "Our results using a shRNA and a Tet-off approach support the notion that ACSL4 up-regulation results in increased breast cancer cell proliferation rate." (PMID 21085606, 2010). "This study was undertaken to determine the role of ACSL4 in AA metabolic pathway in breast cancer cells." (PMID 21085606, 2010). "The acyl-CoA synthetase 4 (ACSL4) is increased in breast cancer, colon and hepatocellular carcinoma." (PMID 21085606, 2010). "We found that ACSL4 mRNA and protein levels correlate with the aggressive phenotype in four different breast cancer cell lines." (PMID 21085606, 2010). "We also found that ACSL4 is significantly up-regulated in the highly aggressive MDA-MB-231 breast cancer cells." (PMID 21085606, 2010). "We found that ACSL4 is significantly up-regulated in highly aggressive breast cancer cell lines, manifested as higher mRNA and protein abundance, as compared to less aggressive phenotypes in breast cancer cells." (PMID 21085606, 2010). "We therefore investigated COX-2 expression levels in the breast cancer cell model used for ACSL4 expression studies." (PMID 21085606, 2010). "Our results provide evidence of the involvement of ACSL4 in the mechanism responsible for the increase in proliferation, invasion and migration shown in breast cancer cells." (PMID 21085606, 2010). "For example, ACSL4 was elevated in radioresistant breast cancer cells." (PMID 41188993, 2025). "As NCOR2 is a transcriptional co-repressor gene, this finding suggests that BQ overexpression competes with NCOR2 to diminish the repression of ACSL4, leading to its upregulation, outlining the mechanism through which BQ modulates ACSL4 expression in breast cancer." (PMID 40507798, 2025). "Our findings suggest that ACSL4 targeting would be a novel approach to suppress breast cancer." (PMID 40507798, 2025). "Further investigation revealed that compound 8 could induce ferroptosis in MCF-7 cells by downregulating the expression of ferroptosis-related genes such as ACSL4 and could combat breast cancer drug resistance by inhibiting ACSL4 protein expression." (PMID 40932861, 2025). "It has been documented that low ACSL4 levels are correlated with a good prognosis in breast cancer." (PMID 39335604, 2024). "Pioglitazone has been reported to inhibit ACSL4 to protect breast cancer cells from ferroptosis, in parallel, pioglitazone functions as a stabilizer of CISD1 to inhibit mitochondrial iron uptake, which dictates another mechanism of pioglitazone in the regulation of ferroptosis." (PMID 38918793, 2024). "For example, genes such as acyl-CoA synthetase long-chain family member 4 (ACSL4) and GPX4 have been shown to serve as independent predictors of chemosensitivity in neoadjuvant chemotherapy for breast cancer, and their expression levels are strongly associated with patient prognosis." (PMID 39759144, 2024).
breast cancer (continued). "Consequently, targeting ACSL4 presents a novel therapeutic strategy for breast cancer, while transferring the basic scientific discoveries into clinical practice poses a significant hurdle." (PMID 39834807, 2024). "Thus, MAP4K4 contributes to radioresistance in breast cancer by acting upstream of ACSL4 to enhance DNA damage response and inhibit apoptosis." (PMID 38548749, 2024). "This hypothesis has been tested in breast cancer cell lines where positive ACSL4 protein expression predicted QNBC status with a sensitivity of 78% and a specificity of 86%." (PMID 37306503, 2023). "In conclusion, we reveal a novel positive regulatory loop between ZEB2 and ACSL4, which promotes LDs storage to meet the energy needs of breast cancer metastasis, and identify the ZEB2–ACSL4 signaling axis as an attractive therapeutic target for overcoming breast cancer metastasis." (PMID 38078907, 2023). "As such, we postulate that measurement of ACSL4 protein expression in breast cancer tissue would differentiate between receptor-positive and receptor-negative cancers, as well as predict which receptor-positive cancers might be resistant to hormonal therapies." (PMID 37306503, 2023). "Forced expression of ACSL4 in breast cancer cells induces resistance to the cytotoxic effects of etoposide, cisplatin, doxorubicin and paclitaxel, possibly mediated by an increased expression of multidrug resistance transporters including ABCC4, ABCC8 and ABCG2." (PMID 37306503, 2023). "ACSL4 (acyl-CoA synthetase long chain family member 4) is a ferroptosis-related gene and is closely involved in the progression of multiple cancers, such as breast cancer, ovarian cancer and glioma." (PMID 36671526, 2023). "Overexpression of ACSL4 contributes to ZEB2-mediated breast cancer invasion." (PMID 38078907, 2023). "Importantly, we observed a strong correlation between ZEB2 and ACSL4 expression levels in clinical breast cancer samples." (PMID 38078907, 2023). "Notably, we demonstrated that ACSL4 depletion significantly suppressed the invasion and migration of breast cancer cells in vitro and in vivo." (PMID 38078907, 2023). "The ability of ACSL4 to induce a more aggressive phenotype suggests it might be a potential target for inhibition in the treatment of breast cancer." (PMID 37306503, 2023). "Based on the fact that ACSL4 is more highly expressed in the more aggressive breast cancer subtypes, it might be expected that ACSL4 status would also function as a prognostic indicator of disease progression and overall survival." (PMID 37306503, 2023). "It is conceivable that those breast cancers expressing high levels of ACSL4 might be particularly sensitive to such inhibition." (PMID 37306503, 2023). "The expression and relationship of ZEB2 and ACSL4 in breast cancer." (PMID 38078907, 2023). "Because ACSL4 is overexpressed in highly invasive breast cancer cells, we hypothesized that ACSL4 is essential for driving breast cancer migration and invasion." (PMID 38078907, 2023). "However, in breast cancer, ACSL4 mRNA expression is significantly less in cancer versus normal tissue." (PMID 37306503, 2023). "Moreover, ACSL4 was found preferentially expressed in a panel of basal-like breast cancer cell lines and predicted their sensitivity to ferroptosis." (PMID 35652069, 2022). "However, another data set of breast cancer showed high expression of ACSL4 and poor prognosis (DMFS: total number, 286; 95% CI, 1.01–2.05, HR, 1.44; Cox P, 0.0432,055)." (PMID 35126480, 2022). "The prognosis of breast cancer predicted by ACSL4 is related to the type of breast cancer." (PMID 35910359, 2022). "ACSL4 expression was significantly higher in breast cancer tissues than that in adjacent tissues." (PMID 35910359, 2022).